TYRO3 (TYRO3 protein tyrosine kinase)
Diseases named in the same sentence as TYRO3 in open-access papers (continued):
Sharing a sentence is not in itself a finding about the gene and the disease.
autoimmune disease (7 papers, 2019 to 2025). A disorder resulting from loss of function or tissue destruction of an organ or multiple organs, arising from humoral or cellular immune responses of the individual to their own tissue constituents. "For all three TAM receptors, RIP is caused by γ-secretase (for AXL, MER, TYRO3) or MMP2 (for TYRO3) (see“sTAM and autoimmune diseases”)." (PMID 40044635, 2025). "Remarkably, studies on Tyro3−/−Axl−/−Mer−/− triple mutant mice (TAM TKOs) have demonstrated that loss of function of the three receptors, Tyro3, Axl, and Mer, dysregulates the immune system, presented by a severe lymphoproliferative disorder accompanied by a broad-spectrum autoimmune disease." (PMID 37469409, 2023). "The TAM receptor tyrosine kinases (Tyro3, Axl and Mertk) and their ligands (Gas6 and Pros1) play a pivotal role in the resolution of inflammation and have been associated with chronic inflammatory and autoimmune diseases." (PMID 30729671, 2019). "TAM (TYRO3, AXL, MER) is a family of RTKs implicated in cancer and autoimmune disorders, for which ED shedding and RIP were reported." (PMID 40044635, 2025). "The study found that Tyro3−/−, Axl−/-, and Mer−/− mice were suffered from chronic inflammation and autoimmune diseases." (PMID 31221818, 2019). "Because the defective functionality of TKRs Tyro3, Axl, and Mer (TAM) results in the abnormal activation of the immune system, it has been postulated that these receptors may be implicated in the development of autoimmune diseases including RA." (PMID 32051695, 2020). "Growth Arrest-Specific 6 (Gas6) and Tyro3, Axl, and MerTK (TAM) receptors are involved in multiple biological processes, including modulation of the immune response, phagocytosis, apoptosis, fibrosis, inflammation, cancer development, and autoimmune disorders." (PMID 39057085, 2024).
hepatocellular carcinoma (7 papers, 2018 to 2026). A malignant tumor that arises from hepatocytes. "Tyro3 has also been linked to Akt signaling and cell survival regulation in e.g., hepatocellular carcinoma." (PMID 31766614, 2019). "Upregulation of TYRO3 in colorectal and sorafenib-resistant hepatocellular cancer cell lines was also associated with increased AKT phosphorylation." (PMID 30501104, 2018). "In patients with hepatocellular carcinoma, TYRO3 expression was significantly associated with higher levels of serum and intratumoral alpha-fetoprotein, which is an independent diagnostic predictor of disease stage, disease progression, and poorer overall survival." (PMID 30501104, 2018). "The human TYRO3 gene was independently cloned from several different types of tumors, including primary teratocarcinoma cells, a hepatoma cell line, and the K562 chronic myelogenous leukemia cell line." (PMID 30501104, 2018). "A derivative of the Huh-7 hepatocellular carcinoma cell line with acquired resistance to the multi-kinase inhibitor sorafenib had increased expression of TYRO3 relative to the parental cell line." (PMID 30501104, 2018). "Inhibition of TYRO3 in the HEP3B hepatocellular carcinoma cell line using siRNA also reduced phosphorylation of ERK1/2 and decreased cyclin D1 levels." (PMID 30501104, 2018). "Similarly, microRNA-7 inhibits Tyro3 expression and is consequently being explored as an RNA-based therapeutic for treating abhorrent Tyro3 overexpression in human hepatocellular carcinoma." (PMID 30980657, 2019). "For example, TYRO3 mRNA levels were increased by 2-fold or greater in approximately 40% of hepatocellular carcinoma patient samples compared to adjacent normal liver tissue and in a panel of human liver cancer cell lines relative to a normal hepatocyte cell line." (PMID 30501104, 2018). "Cyclin D1 levels were also decreased in hepatocellular carcinoma cells expressing TYRO3 siRNA." (PMID 30501104, 2018).
thyroid cancer (7 papers, 2016 to 2025). "We found that DPP4, TIMP1 and TYRO3 were associated with a better prognosis and survival in patients with thyroid cancer, while FABP4, NR4A1 and SNCA were associated with a poor prognosis and survival in patients with thyroid cancer." (PMID 36407322, 2022). "For instance, inhibition of either TYRO3 or AXL via siRNA decreased expansion of thyroid cancer cells in culture and induced apoptosis, but combined inhibition of both receptors had an even greater effect." (PMID 30501104, 2018). "BrdU incorporation was reduced in thyroid cancer cell lines with siRNA-mediated TYRO3 inhibition." (PMID 30501104, 2018). "TYRO3 was absent in normal thyroid tissue, but was ectopically expressed in all human thyroid carcinoma cell lines tested." (PMID 30501104, 2018). "According to a previous report, TYRO3 and AXL were not expressed in normal thyroid cells, but showed remarkably increased expression in thyroid cancer cells, thereby contributing to the resistance of thyroid cancer to existing targeted treatments." (PMID 34721022, 2021).
gastric cancer (6 papers, 2020 to 2025). A primary or metastatic malignant neoplasm involving the stomach. "TYRO3 promoted cell growth and metastasis through Wnt/β-catenin signaling-mediated EMT in gastric cancer, in which TYRO3 silencing distinctively suppressed gastric cancer cells proliferation, invasion, and metastasis." (PMID 38526709, 2025). "To explore the role of MerTK in gastric adenocarcinoma (GAC), we analyzed the expression of MerTK and other TAMR family members Axl and Tyro3 in a panel of gastric cancer cell lines (MKN45, SNU1, SNU5, KATO‐III, NCI‐N87, and AGS)." (PMID 38545840, 2024). "Although emerging evidence has suggested TYRO3 as a potential therapeutic target in various types of cancers, less is known about its role in gastric cancer (GC) development." (PMID 32018224, 2020). "For instance, TYRO3 promotes the proliferation and metastasis of gastric cancer cells through activation of Wnt/β-catenin signaling pathway." (PMID 33148205, 2020). "Dehu Chen found that TYRO3 expression was significantly elevated in gastric cancer tissues." (PMID 37116196, 2023). "We found that C-10 did not induce cell proliferation of a gastric cancer cell line at 500 nM, which is 5- to 10-fold higher than the dose used to induce TYRO3 phosphorylation in cultured podocytes." (PMID 36454644, 2023).
ovarian carcinoma (6 papers, 2015 to 2022). A malignant neoplasm originating from the surface ovarian epithelium. "In particular, inhibition of TYRO3 in cancers, such as bladder, colon, and ovarian cancer, effectively showed anticancer effects." (PMID 34721022, 2021). "In contrast, TYRO3 overexpression has been shown to mediate taxol resistance in ovarian cancer and in general, promote progression of various cancers when overexpressed." (PMID 33059733, 2020). "In ovarian cancer it is known that Tyro3 overexpression analogously can lead to resistance against taxol based therapy and that its inhibition can circumvent this resistance." (PMID 27486820, 2016). "We first checked by real time RT-PCR the expression of Gas6 and Axl, Mer, and Tyro-3 in a panel of human ovarian cancer cell lines." (PMID 26356564, 2015). "Moreover, metformin treatment of ovarian cancer cells significantly decreased both mRNA and protein levels of Axl and Tyro3 in a dose-dependent manner, indicating that metformin suppresses AXL and TYRO3 expression at the transcriptional level." (PMID 36361682, 2022). "Similarly, increased levels of reactive oxygen species induced both TYRO3 expression and AKT phosphorylation in taxol-resistant ovarian cancer cells." (PMID 30501104, 2018).
retinal degeneration (6 papers, 2014 to 2024). Degeneration of the retina. "Together, our data indicate that Tyro3 modifies Mertk-associated retinal degeneration by modulating the phagocytic capability of the RPE." (PMID 26656104, 2015). "We demonstrate that Tyro3 gene dosage modulates the severity of Mertk-associated retinal degeneration." (PMID 26656104, 2015). "Our findings demonstrate that Tyro3 gene dosage modulates Mertk-associated retinal degeneration, provide strong evidence for a direct role for TYRO3 in RPE phagocytosis, and suggest that an eQTL can modify a recessive IPD." (PMID 26656104, 2015). "If the level of Tyro3 modifies Mertk-associated retinal degeneration, mice homozygous for both Mertk and Tyro3 knockout alleles should display more rapid photoreceptor degeneration than those lacking Mertk function alone." (PMID 26656104, 2015). "The authors went on to demonstrate that the RPE of Tyro3129/129 mice had about one-third the amount of TYRO3 protein of Tyro3B6/B6 mice, suggesting a model in which increased TYRO3 protein from the B6 allele suppressed retinal degeneration in all but the periphery of Mertktm1Gkm/tm1Gkm mice." (PMID 38791338, 2024). "Consistent with this hypothesis, it was observed that TYRO3 expression was at ~33% for Tyro3129/129 (e.g., in Mertk-/- V1) relative to Tyro3B6/B6 amounts, and associated with retinal degeneration." (PMID 35969037, 2022). "Consistent with Tyro3 as a modifier gene, the retinal degeneration phenotype was more severe when Mertktm1Gkm/tm1Gkm was crossed with Tyro3−/− (targeted knockout) mice to generate Mertktm1Gkm/tm1Gkm; Tyro3−/− than in Mertktm1Gkm/tm1Gkm; Tyro3129/129 mice." (PMID 38791338, 2024). "Nonetheless, in a complementary approach, we directly targeted Tyro3 in B6 Mertk-/-V2 mice-derived ES cells to unambiguously demonstrate that the simultaneous ablation of Mertk and Tyro3 in B6 mice is necessary and sufficient for retinal degeneration." (PMID 35969037, 2022). "Retinal degeneration manifests only when the function of Tyro3 is concomitantly lost." (PMID 35969037, 2022). "This ~67% expression of TYRO3 prevented retinal degeneration." (PMID 35969037, 2022). "We have previously shown that Tyro3 mouse mutants, Gas6 mouse mutants, and retina-specific Pros1 mouse mutants all have a normal number of PRs at this time; but that Gas6/Pros1 double mutants display PR death and retinal degeneration that fully phenocopies the degeneration of the Mertk mutants." (PMID 25265470, 2014). "Importantly, mice with the genotype Mertk+/+;Tyro3129/129 exhibit a TYRO3 level comparable to that of Mertk-/-;Tyro3129/129 mice, demonstrating that lower expression is a property of the Tyro3129 allele and not secondary to retinal degeneration." (PMID 26656104, 2015). "The biological basis for the differences in retinal degeneration phenotype in the Mertk-/-V1 versus Mertk-/-V2 and Mertk-/-V3 mouse lines can also be trivially explained by a redundancy in phagocytosis provided for by TYRO3 in the absence of MERTK." (PMID 35969037, 2022). "However, the same mertk gene disruption does not cause retinal degeneration in mice of a pure C57BL6 genetic background with high RPE expression of Tyro3, suggesting that Tyro3 can substitute for MerTK in RPE function." (PMID 34440696, 2021). "For example, retinal degeneration seen in these mice, which had been previously ascribed to failure of MERTK-mediated phagocytosis of photoreceptor outer segments, is only present when TYRO3 function is also lost and was not seen in independently generated MERTK knockout mice." (PMID 37958886, 2023).
leukemia (5 papers, 2016 to 2023). A malignant (clonal) hematologic disorder, involving hematopoietic stem cells and characterized by the presence of primitive or atypical myeloid or lymphoid cells in the bone marrow and the blood. "Finally the roles of both AXL and MERTK in leukemia have been well described, but less is known about TYRO3." (PMID 27834816, 2016). "Finally, as TYRO3, AXL, and MERTK are attractive therapeutic targets in leukemia, we will discuss recent advances toward introduction of small molecule inhibitors of MERTK and AXL into the clinic." (PMID 27834816, 2016).
multiple myeloma (5 papers, 2016 to 2025). "Recent advances in gene expression microarray analysis of multiple myeloma involving B-lymphoid stem cells have demonstrated the upregulation of TYRO3 expression levels." (PMID 40088262, 2025). "The number of GAS6+ and MERTK+ bone marrow plasma cells (BMPCs) were significantly increased in myeloma patients compared to healthy controls; whereas AXL and TYRO3 were mainly undetectable in BMPCs of both groups and also in human myeloma cell lines." (PMID 31694201, 2019). "Similarly, samples from patients with primary malignant plasma cell leukaemia and multiple myeloma also showed the transcriptional activity of TYRO3 mRNA." (PMID 40088262, 2025). "Mertk-knockdown by shRNA reduced survival and proliferation of myeloma cells, while Axl- or Tyro3-knockdown did not affect myeloma cell proliferation." (PMID 31694201, 2019).
triple-negative breast carcinoma (5 papers, 2016 to 2024). An invasive breast carcinoma which is negative for expression of estrogen receptor (ER), progesterone receptor (PR), and human epidermal growth factor receptor 2 (HER2). "We identified the TAM (Tyro3, Axl, and MerTK) RTKs as a crucial therapeutic vulnerability in Triple-negative breast cancer (TNBC)." (PMID 38927958, 2024). "Kasikara and coworkers showed that a pan-TAM (Tyro3, Axl, and Mertk) tyrosine kinase inhibitor enhanced the efficacy of anti-PD-1 antibody treatment in a murine model of triple negative breast cancer." (PMID 35011581, 2021). "Some FLT3 kinase inhibitors are dual kinase inhibitors that inhibit the TAM (Tyro3, Axl, Mer) receptor tyrosine kinase family and are used to treat solid cancers such as non-small cell lung cancer (NSCLC) and triple-negative breast cancer (TNBC)." (PMID 34721022, 2021).
acute myeloid leukemia (4 papers, 2017 to 2021). Acute myeloid leukemia (AML) is a group of neoplasms arising from precursor cells committed to the myeloid cell-line differentiation. "In hematologic malignancies, approximately half of acute myeloid leukemia (AML) patient samples expressed TYRO3 mRNA." (PMID 30501104, 2018). "As a member of the TAM receptor family (TYRO3, AXL, MERTK), MERTK is overexpressed in many solid cancers (such as breast cancer, colorectal cancer, and melanoma) as well as in hematological malignancies such as acute myeloid leukemia (AML)." (PMID 34835225, 2021).
autoimmune disorders (4 papers, 2016 to 2024). "TAM triple mutant mice (Tyro3−/−, Axl−/−, Mer−/−) have elevated levels of pro-inflammatory cytokines and are prone to developing lymphoproliferative disorders and autoimmunity." (PMID 27695708, 2016). "The importance of the TAM regulatory mechanisms is evident in mice deficient for TAMs (Tyro3−/−, Axl−/−, Mer−/−), which have elevated levels of pro-inflammatory cytokines, including TNF-α and IL-6, and are prone to developing lymphoproliferative disorder and autoimmunity." (PMID 27695708, 2016).
bladder cancer (4 papers, 2019 to 2022). "Loss-of-function experiments identified a TYRO3-dependency of bladder carcinoma-derived cells both in vitro and in a mouse xenograft model, whereas AXL and MERTK depletion had only a minor impact on cell viability." (PMID 30765874, 2019). "Tyro3 knockdown studies in tumour xenograft models have shown a role for Tyro3 in tumour progression, as well as the association of Tyro3 expression with poor prognosis in, amongst others, colorectal, hepatocellular, breast, and bladder cancers." (PMID 31766614, 2019). "Our results provide a preclinical proof of concept for TYRO3 as a potential therapeutic target in bladder cancer." (PMID 30765874, 2019). "In MGH-U3 bladder cancer cells, which express Tyro3 alone, ProS1 was again the stronger stimulator of Tyro3 and Erk stimulation but additionally stimulated Akt phosphorylation." (PMID 31766614, 2019). "Moreover, inhibitors of either caspase-3/7 (z-IEVD-fmk) or caspase-8 (z-IETD-fmk) significantly reduced the impact of TYRO3 depletion on cell survival, demonstrating the crucial importance of apoptosis regulation for TYRO3 activity in bladder cancer cells." (PMID 30765874, 2019). "TYRO3 was detected at the plasma membrane in several bladder cancer cell lines by flow cytometry, but IHC staining on human bladder tumour sections showed it to be present mostly in the cytoplasm and only weakly expressed at the plasma membrane of tumour cells." (PMID 30765874, 2019). "We investigated the molecular mechanisms underlying the oncogenic dependency on TYRO3 expression in bladder carcinomas, by conducting a comprehensive gene expression analysis with Affymetrix U133 Plus 2.0 arrays, in MGH-U3, RT112 and UM-UC-5 cells transfected with three different TYRO3 siRNAs." (PMID 30765874, 2019). "We then investigated whether this identified role of TYRO3 in bladder cancer cells was relevant to clonogenic cells, by analysing the consequences of TYRO3 knockdown for the anchorage-independent growth of TYRO3-dependent bladder cancer cell lines in vitro and tumour growth in vivo." (PMID 30765874, 2019). "In addition to this cell-autonomous effect in bladder cancer, TYRO3 may also be involved in cell-non-autonomous effects." (PMID 30765874, 2019). "The TAM family of receptor tyrosine kinases (RTKs), which includes TYRO3, AXL and MERTK, has emerged as new therapeutic target in many types of cancer, but their role in bladder cancer has not yet been determined." (PMID 30765874, 2019). "Oncogenic dependency on members of the TAM tyrosine kinase receptor family (TYRO3, AXL, MERTK) has been reported in several cancer types, but their role in bladder cancer has never been explored." (PMID 30765874, 2019). "Out of these cell lines, two were selected as models in which to probe Tyro3 function; one of these was SCC-25 head and neck squamous cell carcinoma cells, which express both Axl and Tyro3 but not MerTK, whilst the other, MGH-U3 bladder carcinoma cells, expresses Tyro3 as a sole TAM receptor." (PMID 31766614, 2019).
pancreatic cancer (4 papers, 2019 to 2023). "Down-regulation of TYRO3 via RNAi in breast, colon, head and neck and pancreatic cancers has been reported to regulate the cellular signaling pathway by reducing the phosphorylation of STAT3, AKT, and ERK." (PMID 34721022, 2021). "The receptor tyrosine kinases TAM family (TYRO3, AXL, and MERTK) are highly expressed in multiple forms of cancer cells and tumor-associated macrophages and promote the development of cancers including pancreatic tumor." (PMID 37475048, 2023).
viral infection (4 papers, 2019 to 2025). "AXL, a member of the TAM (Tyro3, AXL, and Mertk) subfamily of RTKs, is abundantly expressed in lung tissue and has been implicated in viral infections and lung injury." (PMID 41158072, 2025). "Interestingly, here the diminished expression of TYRO3 in CZS cases highlight its role as a signaling receptor associated with inhibition of type I IFN and general innate immune responses, as well described in other viral infections." (PMID 34899713, 2021).